HLA-F (major histocompatibility complex, class I, F)
Diseases named in the same sentence as HLA-F in open-access papers (continued):
Sharing a sentence is not in itself a finding about the gene and the disease.
asthma (4 papers, 2022 to 2025). "The implication of HLA‐F mobilisation on the cell surface in the inflammatory asthma context needs to be addressed as immune effector cell activity is determined by the balance of inhibitory and stimulatory signals received." (PMID 35988034, 2022). "Because of its implication in immune response in inflammatory context, deciphering HLA‐F surface expression in cells involved in asthma pathogenesis, as HBEC and PLT, would contribute to a better understanding of inflammation onset and immune response in chronic lung disease." (PMID 35988034, 2022).
HIV-1 infection (4 papers, 2017 to 2019). The type species of lentivirus and the etiologic agent of acquired immunodeficiency syndrome (AIDS). "We previously demonstrated that HIV-1 infection causes upregulation of HLA-F at a transcriptional level in stimulated CD4+ T cells." (PMID 29184550, 2017). "HLA-F is directly involved in immune functions during HIV-1 infection and confers a beneficial effect on disease outcome." (PMID 30941482, 2019). "Of note, HIV-1 infection increases the transcription of HLA-F mRNA but decreases its binding to KIR3DS1, indicative of a mechanism for evading recognition by KIR3DS1+ NK cells." (PMID 28769934, 2017). "It’s possible to speculate that HIV-1 infection downregulates HLA-F expression on the surface of infected cells but this hasn’t been investigated due to lack of antibody to HLA-F." (PMID 28769934, 2017). "Thus, protective allotypes might differ from susceptible allotypes in their ability to interact as HLA-I OCs with HLA-F in a setting of HIV-1 infection, in turn enhancing or diminishing recognition by KIR3DS1+ NK cells." (PMID 29184550, 2017). "This would indicate a KIR3DS1: HLA-Bw4I80:HLA-F protective axis in HIV-1 infection that is independent of KIR3DL1." (PMID 29184550, 2017). "Open conformers of HLA-F, which are HLA-F heavy chains devoid of peptide and/or β2-microglobulin (β2m), are high-affinity ligands of the activating NK-cell receptor KIR3DS1 and may play a role in limiting HIV-1 infection." (PMID 31921098, 2019). "Thus, the interaction between KIR3DS1 and HLA-F upregulated on HIV-1–infected cells may have similarities to the well-reported upregulation of stress ligands such as ULPBs and MIC-A/MIC-B in HIV-1 infection, which are in turn recognized by the activating NK-cell receptor NKG2D." (PMID 29184550, 2017).
rheumatoid arthritis (4 papers, 2023 to 2025). A chronic, systemic autoimmune disorder characterized by inflammation in the synovial membranes and articular surfaces. "In addition, the three genes (PSMB9, CD74, and HLA-F) were validated in other rheumatologic disorders including systemic lupus erythema (SLE) and rheumatoid arthritis (RA)." (PMID 37153570, 2023).
melanoma (3 papers, 2016 to 2022). A malignant, usually aggressive tumor composed of atypical, neoplastic melanocytes. "Another candidate MTG pair with a potential impact in the melanoma-TME crosstalk identified by our analysis was mir-1914/HLA-F." (PMID 32024530, 2020). "Also favoring an immunosuppressive environment, we identified the circulating mir-1914 representing a putative player in the crosstalk between melanoma cells and the TME, regulating the expression of HLA-F." (PMID 32024530, 2020).
nasopharyngeal carcinoma (3 papers, 2018 to 2024). A carcinoma arising from the nasopharyngeal epithelium. "Using a commercial anti-HLA-F mAb EPR6803 (Abcam, Cambridge, UK), the expression of HLA-F was investigated in nasopharyngeal carcinoma and brain glioma." (PMID 38390869, 2024).
non-small cell lung carcinoma (3 papers, 2019 to 2024). A group of at least three distinct histological types of lung cancer, including non-small cell squamous cell carcinoma, adenocarcinoma, and large cell carcinoma. "HLA-F is a non-classical HLA class I antigen; its expression is associated with poor OS and it is a potential prognostic indicator in patients with non-small-cell lung cancer." (PMID 34257557, 2021).
preeclampsia (3 papers, 2022 to 2025). Preeclampsia is a hypertensive disorder of pregnancy that is characterized by new-onset hypertension with proteinuria presenting after 20 weeks of gestation, and depending on mild or severe forms may initially present with severe headache, visual disturbances, and hyperreflexia. "This study aimed to analyze the effect and mechanism of HLA-F on the proliferation of trophoblast and the underlying mechanism of reduced HLA-F involved in preeclampsia." (PMID 40251569, 2025). "This study may offer novel insights into the mechanisms underlying preeclampsia development and shed light on the metabolic regulatory functions of the classical antigen-presenting molecule HLA-F." (PMID 40251569, 2025). "The regulatory molecule Human Leukocyte Antigen F (HLA-F) has been implicated in trophoblast proliferation during pregnancy, and reduced levels of this antigen have been identified in trophoblast cells of patients with preeclampsia." (PMID 40251569, 2025). "In this context, it seems likely that the decreased expression of HLA-F in the trophoblast of preeclampsia patients may be the result of gene polymorphism." (PMID 40251569, 2025). "However, the potential association between HLA-F gene polymorphisms and preeclampsia remains unexplored and warrants further investigation." (PMID 40251569, 2025). "To confirm previously reported results regarding HLA-F expression at the maternal-fetal interface, we performed HLA-F immunohistochemical staining on samples of placenta obtained from 12 patients with preeclampsia and 12 normal late-pregnancy controls." (PMID 40251569, 2025). "The expression of HLA-F is reduced in extravillous trophoblast and villous cytotrophoblast from patients with preeclampsia." (PMID 40251569, 2025). "Next, we used PCR and Western blot to quantify HLA-F expression in VCT cells obtained from the placenta of preeclampsia patients and normal late pregnancy controls." (PMID 40251569, 2025). "In a previous study, we detected reduced levels of HLA-F in EVT cells of patients with preeclampsia, a pregnancy-specific multi-etiological disorder characterized by maternal hypertension and organ damage." (PMID 40251569, 2025). "These analyses confirmed that the expression of HLA-F mRNA and protein was significantly lower in the placenta of preeclampsia patients than that of late pregnancy controls." (PMID 40251569, 2025). "Recent studies have revealed the reduced expression pattern of HLA-F at the MFI in preeclampsia, while the mechanism of it mediating maternal fetal immune tolerance has not been revealed." (PMID 37854606, 2023). "The functions of HLA-E and HLA-F in pregnancy and preeclampsia are less well-described and warrant further investigation." (PMID 35571013, 2022). "Similarly, via immunohistochemical analysis of placenta decidua, Dunk and colleagues also found that HLA-F protein expression was decreased in the EVT cells of patients with preeclampsia." (PMID 40251569, 2025). "To date, though, the mechanism by which HLA-F reduction might contribute to the pathogenesis of preeclampsia remains unknown." (PMID 40251569, 2025). "Our findings regarding cellular heterogeneity and immune cellular dysfunction, as revealed by scRNA-seq, and the function of HLA-F in cells provide new perspectives for further investigation of their roles in the pathogenesis of preeclampsia, and then provide potential new therapeutic target." (PMID 37854606, 2023). "In addition to immune dysregulation, another potential mechanism linking reduced HLA-F expression to preeclampsia might involve its impact on glycolysis." (PMID 40251569, 2025). "The non-classical HLA class I molecules HLA-F and HLA-G have also been identified as potentially dysregulated in preeclampsia." (PMID 35571013, 2022).
preeclampsia (continued). "In summary, this study presents preliminary evidence that insufficient HLA-F expression in trophoblastic cells leads to a decrease in glycolysis and abnormal trophoblast proliferation by down-regulating the expression and activity of PKM2, ultimately leading to the development of preeclampsia." (PMID 40251569, 2025). "As a first step in this direction, this study used a MiniPDX model to confirm the effect of a PKM2 agonist on the proliferation of HLA-F–knockdown trophoblastic cells, and the results suggest that a PKM2 agonist may represent an avenue to explore the treatment of preeclampsia." (PMID 40251569, 2025). "In the absence of effective intervention strategies targeting the HLA-F gene-phenotype and expression level, it is possible that PKM2 agonists may promote placenta formation and have potential therapeutic value for preeclampsia." (PMID 40251569, 2025).
type 1 diabetes (3 papers, 2016 to 2025). "The upregulation in the expression levels of HLA-E, HLA-F and HLA-G in insulin-containing islets of patients with type 1 diabetes could conceivably be linked to a viral infection where the virus is attempting to shield itself from the immune system." (PMID 31820163, 2019). "This review focuses on the current understanding of the non-classical HLA-I subtypes: HLA-E, HLA-F and HLA-G, within and outside the field of type 1 diabetes, and considers the possible impacts of these molecules on disease etiology." (PMID 31820163, 2019). "Upregulation of HLA-F (at both the RNA and protein level) has been observed in the insulin-containing islets of patients with recent-onset type 1 diabetes when compared with islets from non-diabetic controls [16••]." (PMID 31820163, 2019). "This revealed that HLA-F is expressed at low levels in the islets of non-diabetic controls, but is upregulated in the ICIs of patients with recent-onset type 1 diabetes." (PMID 27506584, 2016).
amyotrophic lateral sclerosis (2 papers, 2022 to 2025). Amyotrophic lateral sclerosis (ALS) is a neurodegenerative disease characterized by progressive muscular paralysis reflecting degeneration of motor neurons in the primary motor cortex, corticospinal tracts, brainstem and spinal cord. "However, it is known that HLA-F also promotes fetal normal growth, and, in addition, this molecule modulates the immune system of the peripheral nervous system; it has been found in amyotrophic lateral sclerosis that HLA-F hinders motor neuron death by its binding to inhibitory KIR3DL2 receptors." (PMID 40332403, 2025). "However, HLA-F has been shown to protect fetus development and has a role at peripheral nervous system: HLA-F recognition by the inhibitory KIR3DL2 receptor prevents motor neuron death in amyotrophic lateral sclerosis physiopathology." (PMID 35925520, 2022).
lung carcinoma (2 papers, 2022 to 2023). "Mechanistically, circCRIM1 bound to the IGF2BP1 protein and then destabilized the HLA-F mRNA, ultimately contributing to the attenuation of lung cancer immune evasion." (PMID 36672208, 2023). "Notably, high expression of HLA-F was related to the poor overall survival of patients with lung cancer, glioma, hepatocellular carcinoma, and nasopharyngeal carcinoma." (PMID 36672208, 2023).
systemic lupus erythematosus (2 papers, 2016 to 2022). An autoimmune multi-organ disease typically associated with vasculopathy and autoantibody production. "Anti-HLA-F IgG, associated with the inflammatory status of systemic lupus erythematosus, may represent a biomarker of primary importance in transplantation, although their exact function has not yet been fully elucidated." (PMID 27701438, 2016).
abortion (1 paper, 2022). the ending of pregnancy by removing a fetus or embryo before it can survive outside the uterus. "All three SNPs in the HLA-F locus regulate the expression level of HLA-F in the secretory endometrium of patients with recurrent abortion (RPL), especially the direction of the A allele of rs2523393 SNP is associated with a better chance of pregnancy." (PMID 36105800, 2022).
acute myeloid leukemia (1 paper, 2021). Acute myeloid leukemia (AML) is a group of neoplasms arising from precursor cells committed to the myeloid cell-line differentiation. "In addition to GM, the constitutive expression of HLA-F was associated with the overall survival of individuals with acute myeloid leukemia (AML) and stomach adenocarcinoma (STAD, data not shown)." (PMID 33867844, 2021).
breast tumors (1 paper, 2020). "To further validate these results, we examined the expression levels of HPSE, HLA-F, and SELL in primary breast tumors with high CDYL2b expression." (PMID 32373210, 2020).
chronic nasopharyngitis (1 paper, 2018). "In our study, there was a higher proportion of HLA-F-positive expression in NPC patients (63/74) compared to chronic nasopharyngitis patients (13/40) with a significant difference (p = 0.000)." (PMID 30510890, 2018). "Overall, HLA-F expression was observed in 63 of 74 (85.1%) NPC and 13 of 40 (32.5%) chronic nasopharyngitis paraffin-embedded tissue sections." (PMID 30510890, 2018). "A statistical significance of HLA-F-positive/-negative expression was observed between NPC and chronic nasopharyngitis lesions (p = 0.000)." (PMID 30510890, 2018).
colon adenocarcinoma (1 paper, 2024). "Moreover, among 19 Hub-MHCsig, HLA-DMA, HLA-DMB, and HLA-DOA were positively correlated with microsatellite instability in colon adenocarcinoma, while TAP2, TAP1, and HLA-F were negatively correlated with microsatellite instability in testicular germ cell tumors." (PMID 38714579, 2024).
Esotropia (1 paper, 2024). A form of strabismus with one or both eyes turned inward ('crossed') to a relatively severe degree, usually defined as 10 diopters or more. "In a GWAS with BBJ (180K), RARB in chromosome 3 and HLA-F in chromosome 6 were suggested as candidates in the combined three-entities group with esotropia, exotropia, and idiopathic superior oblique muscle palsy." (PMID 39000095, 2024). "At the standard significance of p < 5 × 10−8, CDCA7 in chromosome 2 for esotropia, HLA-F in chromosome 6 for exotropia, and DAB1-AS1 in chromosome 1 for idiopathic superior oblique muscle palsy were suggested as candidates in a GWAS with BBJ (180K)." (PMID 39000095, 2024). "Additionally, in a GWAS with BBJ (180K), ACAP2 in chromosome 3 and HLA-F in chromosome 6 were suggested as candidates in the combined group of esotropia and exotropia." (PMID 39000095, 2024).
hepatitis B (1 paper, 2016). "Six of 16 designated HLA-E, HLA-G, and HLA-F haplotypes were shown to be associated with risk for hepatitis B or HCC." (PMID 27243039, 2016). "Four SNPs (rs17875380, rs41557518, rs114465251, and rs115492845), in nonclassical class I alleles, were shown to be associated with altered susceptibility to HBV or HCC, while HLA-F ∗01:04, HLA-G ∗01:05N, and HLA-E ∗01:01 are associated with hepatitis B or hepatitis B complicated with HCC." (PMID 27243039, 2016).
hepatitis C virus infection (1 paper, 2021). A viral infection caused by the hepatitis C virus. "HLA-F, as a recently discovered ligand of KIR3DS1, was shown to activate natural killer cells by binding to KIR3DS1 and has been associated with resolution of hepatitis C virus infection." (PMID 34257557, 2021).
Infertility (1 paper, 2025). "Notably, women with polycystic ovary syndrome (PCOS) showed increased HLA-F expression but lower serum progesterone levels, suggesting that endocrine-immune crosstalk may influence HLA-F–mediated immune regulation and contribute to infertility." (PMID 41321564, 2025).
leprosy (1 paper, 2020). Leprosy is a chronic infectious disease affecting primarily the skin and peripheral nervous system. "When we directly compared LCs between a single leprosy biopsy and a single normal skin biopsy from which we performed bead-based LC enrichment (STAR Methods), we detected elevated expression of IDO1, STAT1, HCAR3, and MHC class I molecules (HLA-A, HLA-B, and HLA-F) in LCs in leprosy infection." (PMID 33053333, 2020).
liver cancer (1 paper, 2011). An epithelial or non-epithelial malignant neoplasm that arises from the liver.
metastatic melanoma (1 paper, 2023). A melanoma that has spread from its primary site to another anatomic site. "In addition, the Kaplan-Meier survival analysis further revealed that the high-expression groups of HLA-C, HLA-E, and HLA-F had a longer survival time among patients with metastatic melanoma." (PMID 37435067, 2023).
osteosarcoma (1 paper, 2023). A usually aggressive malignant bone-forming mesenchymal neoplasm, predominantly affecting adolescents and young adults. "We also detected HLA-F transcript levels slightly higher than the lowest value of normal tissues (brain) in ~40 to 50% of HGG, osteosarcoma, and NRSTS PDXs." (PMID 38318504, 2023). "Furthermore, HLA-F transcript levels were slightly above the lowest value of normal tissues (Br) in two HGG, three osteosarcoma, and two NRSTS PDXs." (PMID 38318504, 2023).
respiratory failure (1 paper, 2025). The significant impairment of gas exchange within the lungs resulting in hypoxia, hypercarbia, or both, to the extent that organ tissue perfusion is severely compromised. "HLA-F regulates immunity by interacting with natural killer cell receptors, engaging in antiviral responses, and reducing the risk and severity of respiratory failure." (PMID 40420582, 2025).
sarcoma (1 paper, 2024). A usually aggressive malignant neoplasm of the soft tissue or bone. "Cell‐cell communication analysis showed that SD3 enriched sarcoma cell subtype sarco_2 had low expression of HLA‐DRA, HLA‐E, HLA‐F and HLA‐A, and high expression of ICAM1 and TGFB1." (PMID 39658531, 2024).
Sepsis (1 paper, 2025). Sepsis is defined as life-threatening organ dysfunction caused by a dysregulated host response to infection. "Early prophylactic interventions to activate IRF1 in sepsis patients, thereby regulating HLA-F, may reduce the risk of ARDS and mortality, especially in severely ill patients." (PMID 40420582, 2025). "In summary, the current study identified IRF1 as a promising biomarker for sepsis-associated ARDS risk and survival, with these effects largely mediated by the downstream HLA-F gene." (PMID 40420582, 2025).
skin cancer (1 paper, 2015). "Lesions from skin cancer patients treated at Taizhou Hopsital of Zhejiang Province served as internal positive and negative (with isotype IgG1) controls for HLA-F expression." (PMID 25435979, 2015).
spontaneous abortion (1 paper, 2023). Expulsion of the product of FERTILIZATION before completing the term of GESTATION and without deliberate interference. "Previous studies have also shown that polymorphisms in the HLA-F gene can modify the expression of HLA-F at the MFI, thereby affecting the pregnancy rate in assisted reproduction and the incidence of spontaneous abortion." (PMID 37854606, 2023).